ATP7B (ATPase copper transporting beta)
Diseases named in the same sentence as ATP7B in open-access papers (continued):
Sharing a sentence is not in itself a finding about the gene and the disease.
tumor (continued). "In short, RBM15‐mediated m6A modification enhanced SRSF1 stability, and SRSF1 promoted ATP7B alternative splicing to inhibit cuproptosis, thereby promoting NSCLC cell proliferation and tumor growth." (PMID 40923717, 2026). "We examined the correlation between ATP7B expression and various TGN markers in normal and tumor tissues." (PMID 41107546, 2026). "To further explore the influence of ATP7B expression on patient prognosis, we analyzed the recurrence‐free survival of HCC patients using ATP7B‐stained tumor samples." (PMID 40761482, 2025). "Given that tumor cells are metabolized through aerobic fermentation, ROS present in the non-immune TME of AOC upregulates the expression of ATP7A and ATP7B by activating the Nrf2 signaling pathway." (PMID 40013141, 2025). "As well, we observed a connection between ATP7B expression and TMB, MSI, and immune infiltration in diverse tumor types." (PMID 38037104, 2023). "For instance, the cuproptosis regulators ATP7B and SLC31A1 are almost exclusively expressed in tumor cells." (PMID 37496994, 2023). "The results revealed that LIAS, DLAT, PDHA1, and CDKN2A were significantly upregulated in LUAD tumors compared to normal tissues, while ATP7B, SLC31A1, FDX1, MTF1, and GLS were significantly downregulated in tumor tissues." (PMID 36983664, 2023). "The under-expression of SLC22A1, SLC22A2, SLC47A1, CTR1, and CTR2 leads to reduce uptake of cisplatin whereas the upregulation of ATP7A, ATP7B, MRP1, MRP2, and MRP4 are responsible for increased efflux of cisplatin out of the tumor cell." (PMID 36715825, 2023). "ATP7B, CDKN2A, FDX1, and SLC31A1 had the lowest expression in tumor cell-enriched region (PanCK-expressing)." (PMID 36618352, 2022). "Among them, 7 genes (DLAT, DLD, GCSH, LIAS, LIPT1, PDHA1, and PDHB) were upmodulated, whereas 3 genes (ATP7B, FDX1, and SLC31A1) were downmodulated in the tumor group in contrast with the normal group (p < 0.05)." (PMID 36046242, 2022). "A heatmap showed that the levels of expression of ATP7B, DLAT, DLD, LIAS, and SLC31A1 were upregulated and the levels of expression of DBT, FDX1, and PDHB downregulated in tumor samples." (PMID 36092880, 2022). "The mechanism by which ATP7B is involved in tumor suppression has not been fully investigated, despite the proposal of several theories." (PMID 40316883, 2025). "ATP7A may suppress tumor cell growth and migration by inhibiting the activity of LOX.ATP7A may promote angiogenesis by combining with VEGFR2.ATP7A or ATP7B can bind to platinum drugs to expel it from cancer cells, producing chemotherapy drug resistance." (PMID 36925927, 2023). "The mechanisms by which the drug hits inhibit ATP7B trafficking remain unclear except for Tranilast, which reduces ATOX1 expression in resistant tumor cells." (PMID 32155756, 2020). "Notably, exosomes from tumor cells have been shown to contain both ATP7A and ATP7B." (PMID 31540259, 2019). "Thus, in the context of CRC, the tumor expression of OCT1, OCT2, OCT3, CTR1 and ATP7B may affect response to FOLFOX-4 chemotherapy." (PMID 26859833, 2016). "Levels of expression of the ATP7B, DLAT, and LIAS proteins were higher, whereas the levels of expression of DBT and PDHB were lower, in tumor samples than in non-tumorous kidney tissue, in accordance with the results of differential mRNA analysis." (PMID 36092880, 2022). "Furthermore, EGCG also down-regulated the expression of ATP7B and MTF1 in tumor tissues without affecting CTR1 expression." (PMID 40136640, 2025).
cancer (57 papers, 2012 to 2026). A tumor composed of atypical neoplastic, often pleomorphic cells that invade other tissues. "The cBio Cancer Genomics Portal (cBioPortal) database was used to examine 32 different TCGA cancer studies for mutations in ATP7B." (PMID 38037104, 2023). "Mutations were the most prevalent alterations in the ATP7B gene among cancers (up to 9.91% of samples in SKCM)." (PMID 38037104, 2023). "Next, the level of ATP7B expression associates with both immune cell infiltration and cancer patient survival, but we need to clarify the role of ATP7B in immune cell infiltration." (PMID 38037104, 2023). "We showed that those peptides that interacted with both Atox1 and MBD 3/4 of ATP7B caused preferential toxicity in cancer cells." (PMID 36299299, 2022). "Elevated ATP7B expression has been observed in a variety of cancers, and its expression is associated with cancer prognosis and treatment outcome with platinum-based chemotherapy." (PMID 36568423, 2022). "Additional evidences implicated ATP7A and ATP7B were found to be overexpressed in some cancer cells with acquired cisplatin resistance." (PMID 32508020, 2020). "Overexpression of ATP7B is associated with resistance of various cancer cells to platinum drugs by increasing drug efflux." (PMID 30659176, 2019). "In our study, the only significant associations with ATM p.Asp1853Asn and ATP7B p.Arg952Lys variants indicated the importance of cell cycle and cellular copper metabolism control systems in the cancer-prone phenotype." (PMID 25591549, 2015). "ATP7B is a type of copper effector transporter, which is a key protein in maintaining copper metabolism and copper homeostasis in cells, and is also associated with some cancer prognostic effects." (PMID 38329437, 2024). "A correlation was observed between TMB or MSI and ATP7B expression in 33 common cancers to assess whether mutations affected the activity of ATP7B." (PMID 38037104, 2023). "ATP7B is associated with immune infiltration and may serve as a biomarker to provide new insights into the prognosis of pan-cancer patients." (PMID 38037104, 2023). "However, our findings of deceased MCM7 expression in ATP7B deficiency cells is consistent with previous observation of overexpression of MCM7 in cancers, which is the opposite extreme for apoptosis." (PMID 23843956, 2013). "Polymerase chain reaction (PCR) array analysis was conducted to determine the correlation between ATP7B and 84 cancer-related genes." (PMID 40316883, 2025). "Our study adds a new experimentally validated target, ATP7B, for miR‐302a‐3p and extends the value of miR‐302a‐3p in cancer management." (PMID 40761482, 2025). "A pan-cancer analysis revealed that ATPase copper transporting beta (ATP7B) negatively correlates with macrophage infiltration in BRCA and is strongly associated with prognosis, immunotherapy response, and disease progression." (PMID 41278297, 2025). "Takamitsu Miyayama and Amila Suraweera found that COMMD1 knockdown decreased ATP7B expression and enhanced the effectiveness of cisplatin and radiotherapy on cancer cells." (PMID 40109870, 2025). "Pan-cancer analysis has revealed that cuproptosis related genes, such as ATP7B, ATP7A, and CDKN2A, harbor high-frequency mutations or abnormal expression patterns in various types of cancer." (PMID 40406488, 2025). "The copper transporters ATP7A and ATP7B primarily mediate drug resistance in cancer cells via two distinct mechanisms." (PMID 40406488, 2025). "ATP7B confers resistance to cuproptosis in cancer stem cells by reducing intracellular copper content and inhibiting cuproptosis." (PMID 40276654, 2025).
cancer (continued). "Although cuproptosis holds significant promise for cancer therapy, the glycolysis-dominated metabolic pattern and the tight regulation of intracellular copper levels by ATP7B in cancer cells limit the occurrence of cuproptosis." (PMID 40382627, 2025). "In terms of other cancers, high expression of ATP7B was found in GBM and was found to be connected with lower OS times of patients with GBM35." (PMID 38671021, 2024). "The ATP7B system that is one of the copper transporter components, is still being explored in the field of cancer." (PMID 38037104, 2023). "We also described a sorting box plot showing the activity levels of ATP7B in 33 different types of cancer: highest activity in READ and lowest activity in SARC." (PMID 38037104, 2023). "ATP7B expression was also examined in 33 human cancers with various immune cell subtypes using the CIBERSORT algorithm to determine its potential mechanism of action." (PMID 38037104, 2023). "Therefore, we speculate that ATP7B is associated with immunotherapy for cancers." (PMID 38037104, 2023). "Based on an analysis of 30 human cancers, ATP7B expression was related to immunostimulatory activity, including ESCA(HHLA2:rho = 0.677, p < 2.2e-16; TNFRSF18:rho = -0.614, p < 2.2e-16)." (PMID 38037104, 2023). "ATP7B is a copper-transporting protein that contributes to the chemo-resistance of human cancer cells." (PMID 38037104, 2023). "Based on a spearman correlation analysis of the TISIDB database, we investigated the relationship between ATP7B expression and immunomodulators in 30 human cancer types, including immunoinhibitory, immunostimulatory, and MHC molecule." (PMID 38037104, 2023). "Our study evaluated the differential expression of ATP7B in cancer and paracancerous tissues based on RNA sequencing data from the GTEx and TCGA." (PMID 38037104, 2023). "ATP7B gene expression levels were examined as predictive factors for 33 cancer types using K-M survival analyses." (PMID 38037104, 2023). "Third, our next goal is to test the efficacy of ATP7B in different types of cancer patients, and determines how it works, through in vivo and in vitro studies." (PMID 38037104, 2023). "Based on an analysis of 30 human cancers, ATP7B expression was related to MHC molecule, including ESCA (HLA-DMA2:rho = 0.422, p < 3.09e-09) and THCA(HLA-A: rho = -0.533, p < 2.2e-16)." (PMID 38037104, 2023). "In this model, ATP7B, a copper transporter, has been shown to contribute to platinum drug resistance in various cancer cells." (PMID 37239150, 2023). "Subsequently, we described a sorting box plot showing the expression levels of ATP7B in 33 different types of cancer: highest expression in READ and lowest expression in DLBC." (PMID 38037104, 2023). "The overexpression of ATP7A or ATP7B can lead to intracellular copper accumulation and cell death with aging-related diseases and various cancers." (PMID 38159257, 2023). "It is noteworthy ATP7A or ATP7B can bind to platinum drugs to expel it from cancer cells, producing chemotherapy drug resistance." (PMID 36925927, 2023). "A network of protein interactions between ATP7B and other proteins was created using the GeneMANIA online tool to investigate cancer development and occurrence." (PMID 38037104, 2023). "The expression of DLAT, LIAS, and ATP7B was negatively correlated with the methylation in most of the cancer types." (PMID 36276096, 2022). "ATP7B is a human copper-transporting P1B-type ATPase that is involved in copper homeostasis and resistance to platinum drugs in cancer cells." (PMID 36070320, 2022). "ATP7B is a key mediator of cellular cisplatin, carboplatin, and oxaliplatin accumulation, these platinum-based drugs are widely used in modern cancer therapeutics." (PMID 35664298, 2022). "In the stemness analysis, STAD was the most striking cancer type, which was positively correlated with the expression of ATP7B, SLC31A1, FDX1, and DLAT." (PMID 36276096, 2022).
cancer (continued). "ATP7B is also upregulated in several cancer forms and is involved in platinum chemotherapy resistance." (PMID 36070320, 2022). "The single-nucleotide variation (SNV) analysis revealed that ATP7B and ATP7A were the two most frequently mutated copper metabolism-related cell death genes in cancer." (PMID 36276096, 2022). "Although existing literature reports indicate that ATP7A and ATP7B, are critical for the cisplatin resistance of cancers." (PMID 34298686, 2021). "In particular, elevated expression of ATP7B has been correlated with a worse outcome of cisplatin chemotherapies in patients with different cancers." (PMID 32155756, 2020). "Studies have revealed a correlation between elevated ATP7B expression and reduced effectiveness of cisplatin chemotherapy in cancer patients." (PMID 32843536, 2020). "In this context, circumventing ATP7B-mediated resistance emerges as an attractive strategy to increase the efficacy of Pt-based cancer therapies." (PMID 32155756, 2020). "In this meta-analysis, we systematically evaluated the relationship between four copper transporters (CTR1, CTR2, ATP7A and ATP7B) that influence cellular platinum accumulation and prognosis of cancer patients who received chemotherapy." (PMID 27980217, 2017). "For instance, cisplatin, a potent anti-cancer agent used against solid tumors of various cancers has been shown to bind to both Atox1 and ATP7B, perhaps processes governing cell resistance against this drug." (PMID 29063292, 2017). "In fact, in some cancers ATP7B expression has been connected to tumor-cell differentiation and alteration of outcome for platinum-based chemotherapy drugs." (PMID 29063292, 2017). "Increased protein levels of ATP7A or ATP7B (both are copper export pumps) were reported to correlate to cisplatin resistance a in several human cancer cell lines examined." (PMID 27806319, 2016). "In this study, we show that ATP7B confers MDR to cancer cells, similarly to ATP7A, by facilitating nuclear efflux and following late endosome drug sequestration." (PMID 26988911, 2016). "ATP7B expression has been reported as a poor prognostic marker in some cancers receiving cisplatin-base chemotherapy." (PMID 26988911, 2016). "According to our analysis and previous reports, ATP7B is expected to be important position in MDR of human cancers clinically as well as cisplatin resistance." (PMID 26988911, 2016). "In this study indicates that ATP7B potentially facilitate doxorubicin efflux from the nuclei and following late endo-lysosomal drug sequestration, and confers drug resistance to cancer cells." (PMID 26988911, 2016). "The influence of copper transporters on the import (CTR1) and efflux of cisplatin (ATP7A and/or ATP7B) has been observed in a variety of human cancer cell lines." (PMID 23613873, 2013). "In addition, ATP7B is often closely related to adverse reactions such as cisplatin resistance in cancer treatment." (PMID 41278297, 2025). "Cisplatin and carboplatin are common chemotherapy drugs, and ATP7B can mediate the resistance of cancer cells to platinum-based chemotherapy drugs, helping to alleviate the stress of cancer cells, resulting in poor benefits of traditional chemotherapy for patients." (PMID 38329437, 2024). "Furthermore, the expression level of ATP7B is closely connected with drug resistance and cancer stemness." (PMID 38671021, 2024). "Cancer cells exhibited a correlation between ATP7B expression and drug sensitivity." (PMID 38037104, 2023). "ATP7B might be an immunotherapeutic and prognostic biomarker based on its involvement in cancer occurrence and development." (PMID 38037104, 2023). "It remains unclear what the molecular mechanisms behind ATP7B are in cancer, as well as its role in human pan-cancer studies." (PMID 38037104, 2023). "We wondered whether immune infiltration occurred in pan-cancer in relation to ATP7B using the CIBERSORT algorithm." (PMID 38037104, 2023).
cancer (continued). "GSEA was performed to identify ATP7B with biological significance in pan-cancer." (PMID 38037104, 2023). "Previous studies have shown that many cancers exhibit platinum resistance due to ATP7B." (PMID 38037104, 2023). "This study clearly indicates that ATP7B could be a biomarker for the prognosis and diagnosis of various cancers, which is very important for developing precise cancer treatment in the future." (PMID 38037104, 2023). "Copper efflux proteins, ATP7A and ATP7B, are also involved in cancer progression." (PMID 36296659, 2022). "ATP7B and ATP7A were the two most frequently mutated copper cell death genes in cancer." (PMID 36276096, 2022). "Here, we provided evidence and expanded on previous results by showing that peptides targeting Atox1 and/or ATP7B MBD3/4 can preferentially elicit cancer cell death when administered in the μM range, owing to an increase in copper concentration within the cell." (PMID 36299299, 2022). "Interestingly, we found most mutational co-occurrence in pan-cancer, such as DLAT and ATP7B mutations, whereas less mutually exclusive mutation events were observed." (PMID 36209249, 2022). "While many mechanisms have been proposed for Pt-drug transport, the high-affinity copper transporter (hCtr1), Cu chaperone (Atox1), and Cu exporters (ATP7A and ATP7B) are also involved in cDDP transport, highlighting Cu homeostasis regulation in Pt-based cancer therapy." (PMID 34201235, 2021). "Likewise, elevated ATP7B levels were correlated with worse treatment outcomes of cDDP in various cancers." (PMID 34201235, 2021). "It is also possible that Cu might enhance either expression or efficacy of the organic cationic transporters (ATP7A and ATP7B) in some unknown way that might facilitate the drug influx in the cancer cells." (PMID 30941331, 2019). "Changes in the localization of ATP7B may influence carcinogenesis and cancer progression." (PMID 41107546, 2026). "However, the molecular mechanism and regulation of ATP7B between pan-cancer and immunity remain a mystery, which may provide therapeutic targets for pan-cancer treatment and overcome chemotherapeutic drug resistance." (PMID 38037104, 2023). "Notably, the increase of ERCC1 expression or of ATP7B and the loss of CTR1 have been all consistently reported as mechanisms of platinum resistance as well as predictors of poor response to platinum-based chemotherapy in cancer patients, including HNSCC." (PMID 33015030, 2020). "Finally, the expression of ATP7B in tumors seems to be related to cisplatin efficacy: expression of ATP7B correlates with cisplatin resistance in human non-small-cell lung cisplatin sensitivity of cancer xenografts." (PMID 24278698, 2012). "The critical link between Cu homeostasis and cancer is perhaps further illustrated by the frequent overexpression of ATP7A and ATP7B in invasive and drug-resistant cancers." (PMID 41304721, 2025). "Research has shown that ATP7B overexpression reduces copper accumulation and accelerates copper efflux, thereby diminishing the efficacy of disulfiram (DSF) in cancer cells." (PMID 40406488, 2025). "In contrast, eight regulators (PDHA1, ATP7A, LIPT1, LIPT2, GLS, ATP7B, GCSH, and CDKN2A) were upregulated in cancer tissues." (PMID 36672336, 2023). "For example, ATP7B was overexpressed in KIRC but under-expressed in THCA, indicating that the mechanisms of copper death in different cancer types were different." (PMID 36276096, 2022). "In contrast to other CGRs, ATP7B, NLRP3, and ATP7A were distinctly hypomethylated in multiple cancers, such as BRCA, LUSC, and LUAD." (PMID 36387247, 2022).